LINC01413 (long independently transcribed non-coding RNA 1413)
Gene: Long non-coding RNA gene on chromosome 15 (57,318,888 to 57,325,050, forward strand). Ensembl gene ENSG00000260172.
Diseases named in the same sentence as LINC01413 in open-access papers:
LINC01413 is named in the same sentence as 3 diseases in open-access papers, as found by Europe PMC text mining. Sharing a sentence is not in itself a finding about the gene and the disease. The quoted sentences say what the papers report.
lymph node metastasis (1 paper, 2020). "Subsequently, we confirmed that an elevated level of LINC01413 expression in CRC tissues was strongly correlated to clinicopathological features, such as tumor size, tumor stage, lymph node metastasis, and distant metastasis, and its association with poor overall survival was also revealed." (PMID 31927328, 2020).
tumor (1 paper, 2020). "These investigations reveal that LINC01413 contributes to tumor metastasis of CRC." (PMID 31927328, 2020). "Moreover, LINC01413 level seemed to be closely related to TNM (tumor, node, metastasis) stages because patients at a more advanced stage usually expressed a high LINC01413 level in contrast to those at earlier stages." (PMID 31927328, 2020).
LINC01413 also shares sentences with these, for which no sentence is quoted: colorectal cancer (1 paper).